WTAP (WT1 associated protein)
Diseases named in the same sentence as WTAP in open-access papers (continued):
Sharing a sentence is not in itself a finding about the gene and the disease.
lung cancer (6 papers, 2021 to 2025). A malignant neoplasm involving the lung. "It has been confirmed that RNA methyltransferases such as WTAP and METTL3 and RNA demethylases such as ALKBH5 and FTO are intimately associated with destructive lung diseases, including different types of lung cancer." (PMID 37936118, 2023). "Data from the ENCORI database showed that WTAP was highly expressed in lung cancer." (PMID 38585432, 2024). "In addition, WT1 associated protein (WTAP) was recognized as the downstream target of miRNA‐433, which provided a new direction for the treatment of non‐small cell lung cancer." (PMID 35976177, 2022). "To investigate how m6A is regulated in KL lung cancer, we compared the expression of proteins that act as the m6A writer complex (METTL3, METTL14, and WTAP) and erasers (ALKBH5 and FTO)." (PMID 34016959, 2021).
asthma (5 papers, 2021 to 2025). "Additionally, the m6A RNA modification machinery including METTL3, METTL14, FTO, YTHDF1/2, IGF2BP2, and WTAP is explored for its emerging significance in regulating post-transcriptional gene expression during asthma progression." (PMID 41008562, 2025). "Moreover, another study on childhood asthma found that m6A regulators also played a crucial role and screened five candidate m6A regulators (FMR1, KIAA1429, WTAP, YTHDC2, and ZC3H13) to predict the risk of childhood asthma." (PMID 35712670, 2022). "An RF model was established to select five candidate m6A regulators (FMR1, KIAA1429, WTAP, YTHDC2, and ZC3H13) from the 21 m6A regulators to predict the occurrence of childhood asthma." (PMID 33763115, 2021). "This mechanistic link is supported by earlier findings (see Section 5.1), where WTAP-mediated m6A modification of AXIN1 mRNA promotes its YTHDF2-dependent degradation, thereby enhancing Wnt/β-catenin signaling and contributing to airway smooth muscle cell proliferation in asthma." (PMID 41008562, 2025). "Considered together, the m6A regulators YTHDF3, YTHDC1, WTAP, FTO, METTL3, and ETTL14 may have a significant effect on the prognosis of asthma, but studies on m6A methylation, severe asthma, and the prognosis of asthma are still in the initial stage and require further exploration by researchers." (PMID 39108751, 2024).
cervical cancer (5 papers, 2022 to 2024). A primary or metastatic malignant neoplasm involving the cervix. "We revealed higher levels of ZC3H13, WTAP, HNRNPC, YTHDF3, and VIRMA were significantly associated with worse outcomes in CESC (HR > 1, blue background), while YTHDC1, YTHDF1 were protective factors of cervical cancer (HR < 1, orange background)." (PMID 35581263, 2022). "Specifically, we found lower expression of METTL3, METTL14, and WTAP transcripts, while RBM15 and ALKBH5 abundance was elevated in cervical cancer cells." (PMID 38665783, 2024). "YTHDC1 and YTHDF1 have anti-cancer effects in cervical cancer, while ZC3H13, WTAP, HNRNPC, YTHDF3 and VIRMA have tumor-promoting effects in cervical cancer." (PMID 35581263, 2022).
diabetes (5 papers, 2021 to 2025). "Abnormal expression of WTAP is discovered in multiple diseases, including cancer or diabetes, to address dysfunctional m6A modification in specific genes." (PMID 40424294, 2025). "Similarly, it is reported that METTL3, FTO, METTL14, and WTAP are up-regulated in diabetes patients." (PMID 33748197, 2021). "Consistently, WTAP plays a key role in maintaining β-cell function by regulating m6A mRNA modification depending on METTL3, and the downregulation of WTAP leads to β-cell failure and diabetes." (PMID 40428320, 2025).
endometrial cancer (5 papers, 2021 to 2024). Primary or metastatic malignant neoplasm involving the endometrium (mucous membrane that lines the endometrial cavity). "A high WTAP expression in endometrial cancer is closely associated with its poor prognosis, and it promotes endometrial cancer cell proliferation, migration, and invasion and inhibits apoptosis." (PMID 36139062, 2022). "WTAP is also associated with chemoresistance in hematological malignancies and endometrial carcinoma by upregulating the expression of MRP1 and P-gp and enhancing the phosphorylation of GSK3β at Ser9." (PMID 36207306, 2022). "We used Western blotting to detect the downregulated expression of WTAP in endometrial cancer stem cells compared to that in Ishikawa cells, while other stem cell indicators, such as CD44, CD133, SOX2 and NANOG, were upregulated in ECSCs." (PMID 39044249, 2024). "In endometrial cancer patients, higher HNRNPC, YTHDC2, WTAP, VIRMA, IGF2BP3, and HNRNPA2B1 expression is closely associated with worse outcomes and advanced stage." (PMID 34616742, 2021). "More recently, the levels of YTHDC2, HNRNPC, and VIRMA were suggested to be negatively correlated, whereas WTAP was positively correlated, with MHC molecules in endometrial cancer." (PMID 34616742, 2021). "Besides, WTAP acts as a tumor suppressor gene by methylating 3'-UTR of CAV-1 and then activating NF-κB signaling pathway in endometrial cancer." (PMID 37325054, 2023).
esophageal cancer (5 papers, 2021 to 2023). A primary or metastatic malignant neoplasm involving the esophagus. "In addition, WTAP upregulation in esophageal cancer is associated with poor prognosis." (PMID 36139062, 2022). "Apparently, WTAP functions as a tumor-promoting factor in the pathogenesis of human esophageal cancer." (PMID 34081626, 2021). "Taken together, as a putative oncogenic gene, WTAP is highly expressed in esophageal cancer cells and regulates cell proliferation and apoptosis under both normoxic and hypoxic conditions." (PMID 34081626, 2021). "WTAP, an oncogene, is overexpressed in esophageal cancer cells." (PMID 36139062, 2022). "Thus, WTAP is a downstream target of miR-758-3p in esophageal cancer cells, and is required for hypoxia-mediated resistance to DDP." (PMID 34081626, 2021). "In addition, higher expression of WTAP in esophageal cancer cells was validated using the GEO database." (PMID 34081626, 2021). "Then, applying the GEPIA and TIMER databases, we illustrated the correlations between WTAP expression and immune infiltration in tumors, especially liver hepatocellular carcinoma (LIHC), and esophageal carcinoma (ESCA)." (PMID 36171885, 2022). "Since overexpression of WTAP markedly reversed the anti-tumor effects of miR-758-3p in hypoxic ECA-109 cells, WTAP is a putative oncogene that promotes esophageal cancer progression." (PMID 34081626, 2021).
prostate carcinoma (5 papers, 2020 to 2023). A carcinoma that arises from epithelial cells of the prostate gland. "There are few pieces of researches focused on mutations in m6A-related genes in prostate cancer, but in AML, mutations in m6A writers such as METTL3, METTL14 and WTAP can enhance progression of leukemia, conferring unfavorable survival outcomes." (PMID 32710725, 2020). "We, therefore examined the role of circPDE5A/WTAP complex in prostate cancer." (PMID 35650605, 2022). "In conclusion, we performed a androgen-responsive circRNAs analysis in prostate cancer patient tissues and identified two important regulatory factors, WTAP and TNRC6, which may involve in circRNA biogenesis." (PMID 34685466, 2021). "Similarly, IGF2BP3 (p < 0.05), HNRNPA2B1 (p < 0.05) and WTAP (p < 0.05) were significantly related to prostate cancer RFS in univariate cox regression analyses." (PMID 32710725, 2020). "However, the role of WTAP in prostate cancer is still poorly understood." (PMID 35650605, 2022). "The expression of METTL3, METTL14, WTAP, and CBLL1 was higher in prostate cancer cells compared to non-malignant prostate cells." (PMID 36835633, 2023).
leukemia (4 papers, 2020 to 2024). A malignant (clonal) hematologic disorder, involving hematopoietic stem cells and characterized by the presence of primitive or atypical myeloid or lymphoid cells in the bone marrow and the blood. "Knockdown of WTAP inhibits cell proliferation, induces apoptosis and enhances myeloid differentiation, and plays a oncogenic role in leukemia." (PMID 34485297, 2021). "Importantly, upregulation of WTAP is not enough to promote the proliferation of leukemia cells when the function of METTL3 is absent, indicating that the oncogenic role of WTAP depends on METTL3 and RNA m6A." (PMID 34485297, 2021).
lymph node metastasis (4 papers, 2021 to 2025). "In this study, WTAP expression level in GC tissues were significantly elevated, and there was a significant correlation between high WTAP expression and advanced age, lymph node metastasis, and a high TNM stage." (PMID 39991580, 2025). "Combined analysis of WTAP and clinicopathological data displayed that the mRNA expression level of WTAP was associated with advanced age, poorly differentiation and high TNM stage, similarly, the protein expression level of WTAP was related to advanced age, lymph node metastasis and high TNM stage." (PMID 39991580, 2025). "The expression of METTL3, METTL14, WTAP, YTHDC2, YTHDF1, and YTHDF2 was remarkably higher in CRPC with lymph node metastasis than in CRPC with bone metastasis, whereas ALKBH5, FTO, and YTHDF3 were substantially decreased in CRPC with lymph node metastasis." (PMID 33403026, 2021).
psoriasis (4 papers, 2022 to 2024). An autoimmune condition characterized by red, well-delineated plaques with silvery scales that are usually on the extensor surfaces and scalp. "Thus, it is suggested that WTAP may be an underlying cause of psoriasis and a potential therapeutic target." (PMID 37091865, 2023). "Moreover, the overexpression of WTAP could be involved in the pathogenesis of psoriasis by regulating cell cycle progression." (PMID 37091865, 2023).
serous ovarian cancer (4 papers, 2021 to 2022). "Mechanistically, WTAP maintains the high-grade serous ovarian cancer phenotype by associating with MAPK and AKT signaling pathways; however, further experimental validation is required." (PMID 36139062, 2022). "In addition, WTAP has been evaluated as a prognostic marker of high-grade serous ovarian cancer and is associated with tumor metastasis." (PMID 35251990, 2022). "In high-grade serous ovarian carcinoma, high expression of WTAP correlated with shorter overall survival, and low expression of WTAP reduced cancer cell proliferation and migration." (PMID 34291082, 2021). "WTAP was also overexpressed in high-grade serous ovarian cancer and correlated with poor prognosis." (PMID 36139062, 2022).
cutaneous melanoma (3 papers, 2021 to 2025). A primary melanoma arising from atypical melanocytes in the skin. "In summary, our findings reveal that WTAP is a downregulated m6A regulator in cutaneous melanoma and plays a tumor-suppressive role by restraining melanoma cell proliferation and migration." (PMID 41301778, 2025). "WTAP was recently identified through bioinformatics analysis as a potential prognostic biomarker in cutaneous melanoma, characterized by lower expression in tumor samples and a positive association with overall survival." (PMID 41301778, 2025). "However, many key regulators, such as WTAP, remain poorly characterized in cutaneous melanoma and warrant further investigation." (PMID 41301778, 2025). "Moreover, WTAP was identified as a valuable prognostic factor and potential molecular target for cutaneous melanoma treatment." (PMID 34291082, 2021). "According to the results of the multivariate Cox regression analysis, three of the seventeen m6A RNA methylation regulators were proved to be the potential prognostic factors of cutaneous melanoma, including ELF3, ZC3H13, and WTAP." (PMID 34291082, 2021). "In addition, WTAP, YTHDC1 and YTHDC2 are widely positively correlated with anti-tumor immune-related genes, while IGF2BP3 is widely negatively correlated with these genes, which may be involved in the immune escape of skin melanoma cells." (PMID 34737950, 2021).
esophageal squamous cell carcinoma (3 papers, 2021 to 2026). Esophageal squamous cell carcinoma (ESCC) is a type of esophageal carcinoma (EC) that can affect any part of the esophagus, but is usually located in the upper or middle third. "In esophageal squamous cell carcinoma (ESCC), WTAP mediates m6A modification on the lncRNA PDIA3P1, which is then recognized by IGF2BP1 to enhance its stability." (PMID 41522342, 2026). "METTL3, WTAP, IGF2BP3, YTHDF1, HNRNPA2B1 and HNRNPC were markedly increased in esophageal squamous cell carcinoma (ESCC) and positively related to the expression of PD-1, whose copy number dynamically affects the enrichment of tumor-infiltrating immune cells." (PMID 36225914, 2022).
head and neck squamous cell carcinoma (3 papers, 2020 to 2024). A squamous cell carcinoma that arises from any of the following anatomic sites: lip and oral cavity, nasal cavity, paranasal sinuses, pharynx, larynx, and salivary glands. "Meanwhile, METTL14 and WTAP are upregulated in head and neck squamous cell carcinoma (HNSCC), which is instructive for prognostic prediction in HNSCC." (PMID 39289775, 2024).
liver fibrosis (3 papers, 2021 to 2023). "In the liver fibrosis mice, the m6A methylation abundance was significantly decreased as well as the expressions of WTAP, ALKBH5 and YTHDF1, and the decreased expression of WTAP has been shown to induce the development of liver fibrosis and promote hepatic stellate cell (HSC) activation." (PMID 37227534, 2023).
lung adenocarcinoma (3 papers, 2020 to 2022). A carcinoma that arises from the lung and is characterized by the presence of malignant glandular epithelial cells. "Among these genes, KIAA1429, HNRNPC, YTHDC2, METTL3, WTAP, YTHDC1, and FTO were down expressed in lung adenocarcinoma, RBM15, ZC3H13, YTHDF1, YTHDF2, and ALKBH5 were up expressed." (PMID 32398949, 2020).
melanoma (3 papers, 2020 to 2025). A malignant, usually aggressive tumor composed of atypical, neoplastic melanocytes. "Additionally, the basal expression level of WTAP appeared to be positively associated with the proliferative and migratory capacities of melanoma cell lines (A375 and A2058)." (PMID 41301778, 2025). "Recent research has emphasized the significance of m6A RNA methylation regulators in melanoma, particularly the role of WTAP." (PMID 41301778, 2025). "Overexpression of WTAP led to a significant reduction in melanoma cell proliferation, while its silencing increased proliferative activity." (PMID 41301778, 2025). "Through further exploration of public databases, we identified KLF9 as a potential target gene through which WTAP exerts its effects in melanoma." (PMID 41301778, 2025). "Subsequently, we confirmed the downregulation of WTAP in melanoma at both the tissue and cellular levels and further discovered a negative correlation between WTAP expression levels and the proliferative and migratory capabilities of melanoma cells." (PMID 41301778, 2025). "This study provides new insight into the context-specific role of WTAP in melanoma and suggests it may serve as a potential biomarker or therapeutic target." (PMID 41301778, 2025). "This strengthens our hypothesis that the tumor-suppressive function of WTAP in melanoma is, at least in part, mediated by its role as an m6A “writer” on KLF9 mRNA." (PMID 41301778, 2025). "Although our rescue experiments demonstrated that KLF9 overexpression counteracted the oncogenic effects of WTAP depletion, KLF9 is a multifunctional transcription factor that may regulate melanoma progression through WTAP-independent pathways." (PMID 41301778, 2025).
systemic lupus erythematosus (3 papers, 2020 to 2024). An autoimmune multi-organ disease typically associated with vasculopathy and autoantibody production. "The first available data were focused on the mRNA expression of m6A writers (METTL3, METTL14, and WTAP), erasers (FTO and ALKBH5) and readers (YTHDF2) in peripheral blood mononuclear cells (PBMCs) from lupus affected patients." (PMID 33807762, 2021).
type 2 diabetes (3 papers, 2020 to 2022). "In a recent study, demethylases FTO have been demonstrated to positively correlate with methyltransferases methyltransferase complex (METTL3, METTL14, and WTAP) in patients with type 2 diabetes." (PMID 32583611, 2020). "Moreover, expression of METTL3, METTL14, and WTAP was reported to be increased in blood from patients with type 2 diabetes (T2D), whilst METTL3 was reported to increase hepatic lipid accumulation through YTHDF2 dependent stabilization of PPARα." (PMID 34950106, 2021).
atherosclerosis (2 papers, 2022 to 2025). A disease characterized by the build-up of fatty material and calcium deposition in the arterial wall resulting in partial or complete occlusion of the arterial lumen. "The experimental results demonstrated the roles of ALKBH5, WTAP and METTL3 in atherosclerotic processes, which are consistent with recent studies on m6A in atherosclerosis." (PMID 40225569, 2025). "In vitro experiments were conducted to further investigate the effects of ALKBH5, WTAP and METTL3 on atherosclerosis." (PMID 40225569, 2025).
autoimmune disease (2 papers, 2022 to 2025). A disorder resulting from loss of function or tissue destruction of an organ or multiple organs, arising from humoral or cellular immune responses of the individual to their own tissue constituents. "While m6A regulators such as WTAP are implicated in inflammatory and autoimmune diseases, the mechanisms governing their expression during innate immune activation remain unclear." (PMID 41096633, 2025).
childhood asthma (2 papers, 2021). "Moreover, in another study on childhood asthma found that m6A regulators also played a crucial role, and screened five candidate m6A regulators (FMR1, KIAA1429, WTAP, YTHDC2 and ZC3H13) to predict the risk of childhood asthma." (PMID 34647423, 2021).
colitis (2 papers, 2023). Inflammation of the colon. "Consistently, m6A methyltransferase WT1-associated protein (WTAP) is required for gut RORγt+ Treg cell function to prevent colitis as well as for T cell activation and survival." (PMID 36599968, 2023). "Besides, the functions of WTAP together with m6A methyltransferase were necessary for thymocyte differentiation, control of peripheral T cell activation-induced death, and prevention of colitis via the activation of intestinal RORγt+ regulatory T cell function." (PMID 38049811, 2023).
diabetic nephropathy (2 papers, 2023 to 2025). "In patients with diabetic nephropathy (DN), WTAP is highly expressed, and WTAP knockdown inhibits the m6A methylation of NLRP3 mRNA to downregulate NLRP3 inflammasome activation, which further induces cell pyroptosis and inflammation." (PMID 37063421, 2023). "WTAP integrates inflammatory-oncogenic processes, driving NLRP3 activation in diabetic nephropathy, enabling epigenetic remodeling through TEX41 degradation in RCC, and defining molecular subtypes in lupus nephritis." (PMID 40895041, 2025).
hepatoblastoma (2 papers, 2022 to 2023). Hepatoblastoma (HB) is a malignant hepatic tumor and is the most common pediatric liver cancer. "We have previously shown that several RNA m6A-mediated genes (i.e., METTL3, METTL14, WTAP, YTHD1, YTHDC1, and ALKBH5) are associated with hepatoblastoma susceptibility." (PMID 35986847, 2022). "Our group has previously reported that many genetic variants of genes encoding RNA m6A and m7G methyltransferase, demethylase, and m6A-reading proteins confer hepatoblastoma susceptibility, including METTL3, METTL4, AlkB homolog 5 (ALKBH5), FTO, YTHDC1, YTHDF1, WTAP, WDR4, and METTL1." (PMID 37531210, 2023).
liver disease (2 papers, 2025). "The expression of AP-2α correlated negatively with the expression of WTAP, YTHDC1 and FASN in liver disease samples." (PMID 40180937, 2025). "Clinically, AP-2α expression negatively correlates with the expression of FASN, WTAP, YTHDC1 and the development of liver disease." (PMID 40180937, 2025).